BRCA1 (BRCA1 DNA repair associated)
Diseases named in the same sentence as BRCA1 in open-access papers (continued):
Sharing a sentence is not in itself a finding about the gene and the disease.
breast cancer (continued). "Other studies evaluating BRCA1 haplotypes have used a combination of the SNPs used in our study to evaluate risk in sporadic breast cancer and interactions with hormonal therapy, but we are the first to have used the 3-SNP haplotype found to be associated with low MBPC in our population." (PMID 21708019, 2011). "Common breast cancer-predisposition alleles may differentially modify breast cancer risk among BRCA1 and BRCA2 mutation carriers." (PMID 22110403, 2011). "We identified a deleterious BRCA1 or BRCA2 mutation in 4.7% of the women with breast cancer." (PMID 22085629, 2011). "We have investigated the relative strengths of using family history and tumour morphology, as well as both criteria together, to select the women with early onset breast cancer most likely to carry BRCA1 mutations (including large genomic alterations) by using the BCFR." (PMID 21281505, 2011). "The clinicopatho- logical features of breast cancer in BRCA1 mutation carriers suggest that BRCA1 may function as a stem-cell regulator." (PMID 23508738, 2011). "For cancer risk reduction trials in the breast for e.g., there are certain conditions in which risk of cancer is so high, as in BRCA1 mutation carriers who have 30%-70% lifetime risk of developing breast cancer that the standard of care is to offer risk reduction mastectomy." (PMID 24212828, 2011). "This classifier allows identification of familial breast cancer cases in patients whose germ line BRCA1-mutation status is unknown or assists in the classification of BRCA1 variants of unknown significance." (PMID 22032731, 2011). "The connection between the BRCA1 mutation and breast cancer is well known." (PMID 21816114, 2011). "Interestingly, triple-negative breast cancers, which share a similar molecular and histopathological profile with BRCA1-mutated breast cancers, have also been found to be sensitive to gemcitabine." (PMID 21771338, 2011). "Furthermore, the RAD51L1 locus was associated with PR-positive breast cancer for BRCA1 mutation carriers and the magnitude of the association was similar to that observed in the general population (A.B. Spurdle, personal communication)." (PMID 22053997, 2011). "Moreover, the IGF-1/IGF-1 receptor axis has also been shown to be involved in the increased risk of early-onset breast cancers in women with mutations in the Breast Cancer Susceptibility gene (BRCA1)." (PMID 21888628, 2011). "Germline mutation of BRCA1 increases the risk of developing breast cancer." (PMID 22016618, 2011). "Known risk breast cancer susceptibility alleles have been genotyped in a large series of female BRCA1 and BRCA2 mutation carriers assembled by the Consortium of Investigators of Modifiers of BRCA1/2 (CIMBA) to evaluate their associations with risk of breast cancer for mutation carriers." (PMID 22053997, 2011). "However, CD133+ cells have been identified in breast cancer cell lines created from Brca1-deficient murine mammary tumours and these cells were highly tumourigenic, expressed common stem cell markers and were resistant to DNA-damaging chemotherapy." (PMID 24212798, 2011). "We have previously reported a novel method of using expression arrays and the Cancer Genetic Markers of Susceptibility (CGEMS) Breast Cancer Whole Genome Association Scan to prioritize IR response genes that potentially modify breast cancer risk in BRCA1 and BRCA2 carriers." (PMID 20174566, 2010). "Furthermore, BRCA1/2 mutation carriers also have a higher rate of pregnancy-associated breast cancer before the age of 50." (PMID 20961453, 2010). "Furthermore, in BRCA1 or BRCA2 carriers with breast cancer, Tamoxifen use was associated with the prevention of secondary and contra lateral breast cancer." (PMID 20961453, 2010).
breast cancer (continued). "Because AKT1 activity is inducible by hormones, it is tempting to speculate that, for certain people, hormonal treatments could lead to high and chronic activation of AKT1, thus altering the functions of BRCA1, and therefore to predispose to breast cancer." (PMID 21321378, 2010). "Approximately half of all hereditary breast cancers are due to loss of BRCA1 or BRCA2 function." (PMID 20630075, 2010). "For subgroups defined by mutation status of the index case, the non-breast cancers SIR for relatives of the index cases who carried BRCA1 mutations was marginally elevated while the SIR for relatives of the index cases who carried BRCA2 mutations was not elevated." (PMID 20877337, 2010). "In addition, the segregation analysis of Antoniou and colleagues estimated similar polygenic variances of breast cancer risk for BRCA1 and BRCA2 mutation carriers." (PMID 20482762, 2010). "Observed BRCA1 variants in breast cancer cases diagnosed before age 40 in the ABCFS." (PMID 20807450, 2010). "First, BRCA1 associated breast cancers are known to have pushing borders." (PMID 20398395, 2010). "Haploinsufficiency of BRCA1 may predispose both to the development of breast cancer as well as to a specific histopathologic and or immunohistochemical profile." (PMID 21080930, 2010). "However, testing for differences between BRCA1-associated ER+ cancers with a retained wt BRCA1 and ER+ sporadic breast cancers would require larger numbers of these ER+ BRCA1 cancers as well as age matched ER+ sporadic controls." (PMID 21080930, 2010). "In BRCA1 mutation carriers, breast cancers mostly exhibited a basal-like molecular phenotype." (PMID 21059199, 2010). "Interestingly, the molecular portrait of premalignant tissue from BRCA1 mutation carriers, who usually develop basal-like breast cancers, showed striking similarity to the luminal progenitor signature." (PMID 20346151, 2010). "Furthermore 60%-70% of hereditary breast cancers seem to arise secondary to germline mutations in the BRCA1 and BRCA2 genes." (PMID 20961453, 2010). "The BRIP1 gene (BRCA1 interacting protein-1) encodes a protein that is a DNA/RNA helicase of the REC Q family that binds to the carboxy-terminus of BRCA1 protein conferring an activity involved in DNA repair and variants of this gene can predispose to breast cancers." (PMID 20111735, 2010). "In addition, point mutations in the BRCT domain derived from patients with inherited breast cancer result in loss of transcriptional activity, and BRCA1 can also function as a negative regulator on some gene promoters." (PMID 20160719, 2010). "Although the available evidence is not sufficient to decisively conclude that the clinical outcome of women with BRCA1/2-associated breast cancer differs significantly from those of women with sporadic tumours, BRCA1-associated breast cancer often manifests adverse outcome features." (PMID 20877358, 2010). "Thus, reliable determination of the status of the wt BRCA1 allele was possible in 77 BRCA1-associated breast cancers (42 ER+, 35 ER-)." (PMID 21080930, 2010). "The cell of origin for BRCA1-associated breast cancers is still being determined." (PMID 20149218, 2010). "Notably, the later the age at breast cancer diagnosis, the greater the relative change in the BRCA1 mutation carrier probability." (PMID 20482762, 2010). "Approximately half of hereditary breast cancers have mutations in either BRCA1 or BRCA2." (PMID 20614009, 2010). "Somatic BRCA1 mutations are rarely observed in sporadic breast cancer; however epigenetic downregulation of BRCA1 has been reported in approximately 30% of sporadic breast cancers and 70% of ovarian cancers." (PMID 20209131, 2010).
breast cancer (continued). "Microarray analysis has been reported to successfully predict estrogen receptor and lymph-node status of breast cancer, to distinguish between cancers associated with BRCA1 or BRCA2 mutations and to identify subclasses of breast cancer and predict outcome based on gene expression patterns." (PMID 20840765, 2010). "The issue of whether ER+ BRCA1-associated breast cancers demonstrate LOH for the wild-type (wt) BRCA1 allele has been investigated." (PMID 20149218, 2010). "In some sporadic breast cancers, the poor outcome associated with BRCA1 methylation and low expression levels could be explained by MYC amplification." (PMID 20209131, 2010). "An incorrect repair of DNA double-strand breaks after IR, due to BRCA1/2 mutation, could lead to the development of new primary breast cancer." (PMID 20074364, 2010). "Correspondingly, the manifestation of a basal-like phenotype by BRCA1 inactivation has been shown in breast cancer cells and corroborated in animal studies by multiple groups, providing further support for the association between BRCA1 pathway disruption and basal-like breast carcinomas." (PMID 24281106, 2010). "This differs from researchers and clinicians who are of the opinion that risk-reducing surgery is the best way to eradicate breast cancer risk in BRCA1/2 mutation carriers and have voiced their concern that some women are waiting too long to decide about RRM and RRO." (PMID 20687957, 2010). "Recently, it has been demonstrated that a defect in homologous recombination can lead to changes in drug sensitivity profile, rendering the BRCA1 deficient breast cancers sensitive to mitomycin C, cisplatin, etoposide and other drugs that produce double-stranded lesions." (PMID 20585447, 2010). "In some settings, such as breast cancer associated with BRCA1 or BRCA2 mutations, allelic expression imbalance may underlie increased disease risk." (PMID 20470418, 2010). "Analysis of breast cancer risk-associated SNPs identified by a large population-based GWA study of breast cancer has shown that several of these SNPs also appear to modify risk in BRCA1 and/or BRCA2 mutation carriers." (PMID 21114847, 2010). "In our study, four affected index cases had mutation in BRCA1 gene, their mothers were died from breast cancer before the beginning of the genetic testing, and they might be obligate carriers for BRCA1 mutation." (PMID 20579331, 2010). "We studied 2208 parents and siblings of 504 unselected population-based Caucasian women with breast cancer diagnosed before age 35 years (103 from USA, 124 from Canada and 277 from Australia), 41 known to carry a mutation (24 in BRCA1, 16 in BRCA2 and one in both genes)." (PMID 20877337, 2010). "For families with multiple cases of breast cancer currently attending cancer genetics services in Australia, at most 20% of those screened for BRCA1 and BRCA2 are found to carry mutations, which is similar to the rates in the United Kingdom and the United States." (PMID 21182766, 2010). "Basal type tumours are particularly prevalent in BRCA1 associated breast cancer." (PMID 20146796, 2010). "In addition, 31 patients with early onset breast cancer and a family history of breast or ovarian cancer were analyzed for mutations in BRCA1." (PMID 20380699, 2010). "For example, it is already known that a breast cancer attributable to a mutation in the BRCA1 gene may have different tumour characteristics, different recurrence risks and possibly different treatment implications." (PMID 20180951, 2010). "In addition, several clinical studies have shown a better clinical response to anthracycline- and cyclophosphamide- containing regimens in BRCA1 mutation carriers than in sporadic breast cancer patients." (PMID 20209131, 2010).
breast cancer (continued). "However, the number of breast cancer patients with mutation screening and pathology information was too small to estimate directly the precise contribution of BRCA1 and BRCA2 mutations to the FRRs by tumour subtype." (PMID 20146796, 2010). "Haploinsufficiency of BRCA1 may predispose both to the development of breast cancer as well as to a more limited histopathologic profile." (PMID 20149218, 2010). "It is of interest, however, that when utilizing an agnostic approach in BRCA2 mutation carriers in this study, the major determinants of risk variation in mutation carriers are those that also modify risk in subsets of sporadic, BRCA1/2 wild type, breast cancer." (PMID 21060860, 2010). "DNA sequence variants of unknown clinical significance are regularly identified when individuals with a family history of breast cancer are screened for mutations in the BRCA1 and BRCA2 genes." (PMID 20507642, 2010). "Furthermore, several retrospective breast cancer studies have confirmed that carriers of BRCA1 mutations gained more benefit from DNA-damage-based chemotherapy." (PMID 20209131, 2010). "Our findings suggest that many of the newer therapies for BRCA1 breast cancers designed to exploit the BRCA1 deficiency in these cancers may also be effective in ER+ cancers that develop in this population." (PMID 21080930, 2010). "Deficiency of normal BRCA1-mediated double-stranded DNA repair function predisposes female carriers to early development of ovarian cancer and, more commonly, to a highly aggressive form of breast carcinoma." (PMID 24281106, 2010). "In multiple experimental systems including primary mammary tumors, cultured human cells, and Brca1-deficient mice, Shukla and colleagues showed that BRCA1 deficiency resulted in increased expression of IRS1, IGF1R and IGFBP2, and increased levels of serum IGF1." (PMID 19843326, 2009). "In addition, it was found that pregnancy is a risk factor of development of breast cancer among carriers of BRCA1 and BRCA2 genetic mutations." (PMID 19254357, 2009). "In addition, a chemical inhibitor of EZH2, 3-deazaneplanocin A (DZNep), is about 20-fold more effective in killing BRCA1-deficient cells compared to BRCA1-proficient mammary tumor cells." (PMID 19709408, 2009). "In approximately 15% of the DNA mutation scannings of BRCA1 or BRCA2 in breast cancer families, the test result is difficult to interpret because an unclassified variant is found (UV, or 'variant of uncertain clinical significance' (VUCS) or 'variant of uncertain significance' (VUS)." (PMID 19563646, 2009). "In the present study, we have identified 26 carriers of a BRCA1 germ-line mutation among a hospital-based series of 987 breast cancer patients unselected for family history, specifically screened for the four most common BRCA1 mutations in the Greek population." (PMID 19491894, 2009). "Approximately 10% of cases of epithelial ovarian cancer (EOC) are associated with a clear hereditary predisposition to disease; the vast majority of cases resulting from inherited alterations in the breast cancer-associated tumor suppressor genes 1 or 2 (BRCA1 or BRCA2) (reviewed in:)." (PMID 20046879, 2009). "This would indicate that EZH2 constitutes a therapeutic target for BRCA1-deficient breast cancer." (PMID 19709408, 2009). "BRCA1/2 mutation carriers have an estimated lifetime risk of breast cancer between 45%–82%." (PMID 19602282, 2009). "For BRCA1 only, a mutation frequency of 0.4% is found in Finnish, 2.1% in Dutch, 3% in Polish, <1% in Swedish, 1.5% in Brazilian, and 2.4–3.5% in US unselected breast cancer patients." (PMID 19491894, 2009). "Between 4% and 40% of male breast cancers might result from autosomal dominant mutations, primarily BRCA1 or BRCA2 mutations." (PMID 19144122, 2009).
breast cancer (continued). "Mammographic density, a strong risk factor for breast cancer, has been positively associated with the ratio of IGF1 to insulin-like growth factor binding protein (IGFBP)-3 in premenopausal women, and has been shown to modify the breast cancer risks in BRCA1 and BRCA2 mutation carriers." (PMID 19843326, 2009). "A study on the effects of interventions to prevent inherited breast cancer in prospectively ascertained breast cancers in screened women at family history clinics, indicated that BRCA1 mutation carriers have less effect of early diagnosis and treatment compared to other groups." (PMID 19366445, 2009). "Women who carry a germline mutation of BRCA1 frequently develop breast cancer at an early age." (PMID 19718449, 2009). "Germline mutations in the breast cancer genes BRCA1 and BRCA2 are related to an increased risk for breast, ovarian and other cancers in a syndrome known as hereditary breast and ovarian cancer (HBOC) which accounts for most cases of hereditary breast cancer (HBC) worldwide." (PMID 21637504, 2009). "To address this matter, we believe that the simplified BRCA1 screening for the four most prevalent Greek mutations designed and employed here should be offered to more women with breast cancer, especially those with an early disease onset and ideally to all breast cancer patients." (PMID 19491894, 2009). "It regulates BRCA1, the obnoxious breast cancer susceptibility gene." (PMID 19919702, 2009). "In this study we aimed to evaluate the role of a SNP in intron 1 of the ERCC4 gene (rs744154), previously reported to be associated with a reduced risk of breast cancer in the general population, as a breast cancer risk modifier in BRCA1 and BRCA2 mutation carriers." (PMID 19920816, 2009). "A substantial part of all hereditary breast cancer cases is caused by BRCA1 germline mutations." (PMID 19904273, 2009). "Other BRCA1 founder mutations are relatively rare in Russian ovarian or breast cancer cases." (PMID 19338682, 2009). "Consistent associations were found for BRCA1 and/or BRCA2 mutation carriers, indicating that SNPs involved in the susceptibility to develop breast cancer in the general population are good candidates to be tested as potential modifiers in BRCA1 and BRCA2 mutation carriers." (PMID 19920816, 2009). "Thus different results as to the effect of MDM2 309 SNP on breast cancer onset age in BRCA1/2 mutation carriers and in the non carrier control Ashkenazi group were obtained by different groups." (PMID 19226467, 2009). "We also investigated the existence of any significant association between mutations in BRCA1-2 genes and phenotypic characteristics of breast cancer patients that could drive specific treatment and influence the process of mutation testing." (PMID 19619314, 2009). "In addition, BRCA1-associated breast cancers frequently show a low prevalence of HER2 overexpression or amplification." (PMID 19818148, 2009). "The mRNA expression of ERα was investigated to understand whether increased hormone sensitivity was a mechanism for development of breast cancer in BRCA1 mutation carriers." (PMID 19445691, 2009). "There were insufficient numbers of known BRCA1/2 mutation carriers within this group of women to determine whether mutation carriers differ in measures of pain from other women at high risk of breast cancer." (PMID 19602282, 2009). "Based on sound preclinical evidence for increased sensitivity of BRCA1-deficient breast cancer cells to platinating agents, this Polish-Canadian research team has taken a risk of recruiting potentially operable and yet chemonaive breast cancer patients for the study." (PMID 19379506, 2009). "Moreover, the knock-down experiments show that BRCA1-deficient mammary tumor cells are dependent on EZH2 for their survival." (PMID 19709408, 2009).